EZH2 (enhancer of zeste 2 polycomb repressive complex 2 subunit)
Diseases named in the same sentence as EZH2 in open-access papers (continued):
Sharing a sentence is not in itself a finding about the gene and the disease.
colorectal cancer (continued). "Here we screened a sgRNA library to identify epigenetic regulators responsible for the vulnerability of colorectal cancer (CRC) cells to glucose deprivation and found that more EZH2-knockout cells survived glucose deprivation." (PMID 34671029, 2021). "In colorectal cancer, SNHG6 participated in the suppression of pro-apoptosis gene p21 through EZH2, which thus promoted tumor progression." (PMID 33431838, 2021). "In patients with high MALAT1 expression, it was found that MALAT1 binds EZH2 to the CDH1 promoter and inhibits miR-218 during oxaliplatin treatment, indirectly promoting EMT, metastasis, and chemoresistance of colorectal cancer cells." (PMID 34199840, 2021). "Our results are consistent with the findings that EZH2 expression is elevated in CSC subpopulation and EZH2 promotes the expansion of CSCs in breast and colorectal cancer." (PMID 32127003, 2020). "We confirmed this result by inhibiting OGT and/or EZH2: respectively with Ac5S-GlcNAc (Ac5S) and GSK343 specific inhibitors and validated them also in LS174T human colorectal cancer cell line." (PMID 33126652, 2020). "As we expected, RIP results revealed that SNHG1 bound with EZH2, SUZ12 and EED in colorectal cancer cells." (PMID 30266084, 2018). "Supporting this broader implication, EZH2 and TSP1 expression negatively correlates with each other in several large TCGA solid tumor datasets, such as breast, stomach, and colorectal cancers, as well as lung squamous carcinoma." (PMID 30287808, 2018). "Moreover, low EZH2 expression was associated with a shorter PFS in patients with colorectal cancer, independent of gene mutations in the downstream part of the EGFR pathway and miR-31 expression, suggesting that EZH2 expression is a useful and additional prognostic biomarker for anti-EGFR therapy." (PMID 28147317, 2017). "We researched the correlation between PRC2 and BLACAT1 by RNA immunoprecipitation (RIP) in colorectal cancer cells, then we observed that endogenous BLACAT1 was significantly enriched in the anti-EZH2 RNA-IP fraction." (PMID 28277544, 2017). "Long non-coding RNA HOXA-AS2 represses P21 and KLF2 expression transcription by binding with EZH2, LSD1 in colorectal cancer." (PMID 29221147, 2017). "In colorectal cancer, incRNA BLACAT1 can repress p15 expression by binding to PRC2 (EZH2 part), thus contributing to the regulation of CRC cell cycle and proliferation." (PMID 29254174, 2017). "To determine whether colorectal cancer cells respond to EZH2 inhibition and to explore which factors influence the degree of response, we treated a panel of 20 organoid lines derived from human colon tumors with different concentrations of the EZH2 inhibitor GSK126." (PMID 27634879, 2016). "EZH2, MFGE8, and miRs expression levels in plasma and FFPE samples, and OS in colorectal cancer patients were evaluated." (PMID 25081869, 2014). "Next, we tested the effect of RNAi-mediated EZH2 repression on the growth of HCT116, LoVo, and DLD1 colorectal cancer cells." (PMID 21765901, 2011). "Furthermore, PRMT5 functionally interacts with EZH2 to suppress CDKN2B expression through epigenetic mechanisms, promoting colorectal cancer (CRC) progression." (PMID 39043634, 2024). "We demonstrate a negative correlation between EZH2 and class II expression in colorectal cancer in TCGA dataset, in addition to the negative correlation between EZH2 and CXCL9/10 described previously." (PMID 37565053, 2023). "Furthermore, lncRNA LINC00114 can induce EZH2/DNMT1 to reduce miRNA-133b expression and promote colorectal cancer progression." (PMID 35236381, 2022).
colorectal cancer (continued). "This process requires a novel LncRNA, ENSG00000274093.1, which binds to HDAC2 and may act as a modular scaffold for the HDAC1/HDAC2 and EZH2 complexes, thereby altering EMT in colorectal cancer cells." (PMID 33325150, 2021). "Upregulated EZH2 could mediate the H3K27me3 in the promoter of SEMA3F, which promoted colorectal cancer development." (PMID 34512145, 2021). "In colorectal cancer, LINC00114 also binds and recruits both EZH2 and DNMT1." (PMID 33050646, 2020). "Enhancer of zeste homolog 2 (EZH2) is a subunit of the polycomb repressive complex 2 (PCR2) and high level of EZH2 has been observed in different cancers including bladder cancer, non-small-cell lung cancer as well as colorectal cancer." (PMID 31055775, 2020). "One important point of concern in this meta-analysis is that there was no multivariate analysis conducted to assess EZH2 as an independent prognostic factor for colorectal cancer." (PMID 33050946, 2020). "Importantly, EZH2 has been reported to be related to 3′-end of MALAT1 and down-regulate the expression of E-cadherin in colorectal cancer." (PMID 31174563, 2019). "Besides, through analyzing colorectal cancer RNA sequencing data in TCGA, we found SNHG1 expression was positively correlated with EZH2, SUZ12 and EED." (PMID 30266084, 2018). "Thus, accumulating evidence suggests that EZH2 is a useful and additional prognostic biomarker for anti-EGFR therapy in patients with colorectal cancer." (PMID 28147317, 2017). "EZH2 expression scores of 0 (negative), 1 (weak), 2 (moderate), and 3 (strong) were observed in 11%, 21%, 18%, and 50% of the colorectal cancer tissues, respectively." (PMID 28147317, 2017). "Moreover, PVT1 expression was up-regulated in colorectal cancer tissues, which correlated with the expression of MYC and many MYC regulating genes FUBP1, EZH2, and NPM1." (PMID 29108264, 2017). "EZH2 expression scores of 0 (negative), 1 (weak), 2 (moderate), and 3 (strong) were observed in 15%, 19%, 25%, and 41% of the colorectal cancer tissues, respectively." (PMID 26871294, 2016). "Taken together, our results suggest that EZH2 plays a critical role in autophagy and apoptosis in the progression of CRC, which potentially facilitates the development of an ideal strategy for combating colorectal cancer." (PMID 27706111, 2016). "EZH2 expression in colorectal cancer tissues was significantly higher than its expression in normal mucosa tissues (P < 0.0001)." (PMID 26871294, 2016). "Collectively, our study indicated that downregulation of the epigenetic gene EZH2 may contribute to eliminate the CRC cells, which may provide a potential mechanism for the treatment of colorectal cancer." (PMID 27706111, 2016). "Moreover, some studies showed that high expression of EZH2 was the better prognostic factor in non-small-cell lung cancer (NSCLC) and colorectal cancer (CRC)." (PMID 26683709, 2016). "It is evident that apoptosis and autophagy of tumor cells is crucial for the tumorigenesis and progression of cancer, however, the exact role of EZH2 plays in apoptosis and autophagy has not been fully elucidated in colorectal cancer (CRC)." (PMID 27706111, 2016). "In the current study, negative, weak, moderate, and strong EZH2 expressions were observed in 15%, 19%, 25%, and 41% of colorectal cancers, respectively." (PMID 26871294, 2016). "High expression of SNHG1 in patients with colorectal cancer can interact with EZH2 to regulate histone methylation of Krüppel-like factor 2 (KLF2) and cyclin-dependent kinase inhibitor 2B (CDKN2B) in the nucleus and affect the biological behavior of colorectal cancer cells." (PMID 40226409, 2023). "Epigenetic control of autophagy by methyltransferases has been reported in the setting of colorectal carcinoma where the methyltransferase EZH2 inhibits several negative regulators of mTOR (mechanistic target of rapamycin [serine/threonine]) leading to inhibition of autophagy." (PMID 35710782, 2022).
colorectal cancer (continued). "Thus, our study has identified a novel LncRNA, ENSG00000274093.1, which bound HDAC2, HDAC1 and EZH2, and may act as a modular scaffold of HDAC1/HDAC2 and EZH2 Complexes, and consequently altered EMT of the colorectal cancer cell." (PMID 33325150, 2021). "However, no study has reported the potential role of EZH2 in the regulation of miR-31 expression in colorectal cancer." (PMID 26871294, 2016). "Thus, accumulating evidence indicates that EZH2 may downregulate miR-31 expression in human cancers; however, no study has reported the relationship between EZH2 and miR-31 in colorectal cancer." (PMID 26871294, 2016).
bladder cancer (159 papers, 2012 to 2026). "A total of 115 bladder cancer patients and 115 healthy control individuals were included in ROC curve analyses to assess the diagnostic performance of serum EZH2 levels for detecting bladder cancer." (PMID 38476362, 2024). "To assess the diagnostic performance of serum EZH2 in detecting bladder cancer, we plotted receiver operating characteristic (ROC) curves and calculated their corresponding area under the curve (AUC)." (PMID 38476362, 2024). "Herein, the collaborative regulatory roles and underlying mechanisms of SIRT7 and EZH2 in CDDP resistance in bladder cancer were explored." (PMID 39719443, 2024). "Fourthly, we did not explore the underlying mechanisms that associated with the elevated levels of serum EZH2 in bladder cancer patients, which is a field that deserves further study." (PMID 38476362, 2024). "H19 has been shown to associate with EZH2 and increase bladder cancer metastasis, or as an miRNA sponge to enhance the expression of oncogenes." (PMID 36578923, 2022). "Bladder cancer with KDM6A mutation increased susceptibility of EZH2 inhibitor through activation of natural killer cell signaling." (PMID 35784457, 2022). "The results herein suggest that subgroup analyses of these and other EZH2 inhibitor trials should focus on patients with bladder cancer with ARID1A-deficient tumors." (PMID 35852858, 2022). "H19 also increases bladder cancer metastasis by associating with EZH2 and inhibiting E-cadherin expression." (PMID 36578923, 2022). "For example, as a part of the complex, lncRNA H19 associated with EZH2 enhancer and inhibited E-cad expression, which resulted in the activation of the Wnt/β-catenin pathway enhancing bladder cancer metastasis." (PMID 31143372, 2019). "Similar to rhabdoid and ovarian tumors with SWI/SNF mutations, complete loss of KDM6A protein sensitizes bladder cancer cell lines and patient-derived xenografts to EZH2 inhibition." (PMID 30692641, 2019). "Here we show that EZH2 inhibition is most effective in bladder cancer cells with both SWI/SNF family member and KDM6A mutations, and is capable of augmenting cisplatin response." (PMID 30692641, 2019). "We exploit the loss of function mutations in KDM6A and SWI/SNF complex to make bladder cancer cells susceptible to EZH2-based epigenetic therapy that activates an immune response to drive tumor cell differentiation and death." (PMID 30692641, 2019). "H19 has been reported to enhance bladder cancer metastasis by associating with EZH2 and inhibiting E-cad expression." (PMID 30517191, 2018). "Such as, long non-coding RNA H19 increased bladder cancer metastasis by associating with EZH2 and inhibiting E-cadherin expression." (PMID 29113337, 2017). "The lncRNA UNMIBC physically associates with EZH2 and is associated with recurrence of primary invasive bladder cancer." (PMID 28410242, 2017). "A previous study reported that lncRNA H19 suppressed the expression of the target gene by associating with EZH2 in bladder cancer." (PMID 27845892, 2016). "H19 increases bladder cancer metastasis by associating with EZH2, which increases Wnt/β-catenin activation and results in a decreased expression of E-cadherin." (PMID 27613832, 2016). "H19 levels are remarkably increased in bladder cancer tissues, and upregulated H19 enhances bladder cancer metastasis by associating with EZH2 and inhibiting E-cad expression." (PMID 26376677, 2015). "Novel approaches to treating SWI/SNF complex mutations in bladder cancer in the future might involve the utilisation of immune checkpoint inhibitors, signalling pathway inhibitors, EZH2 inhibitors, among others." (PMID 39779467, 2025). "Therefore, EZH2 holds the potential as a diagnostic and prognostic biomarker for bladder cancer, offering new insights into the disease’s initiation, progression, and response to treatment." (PMID 38476362, 2024).
bladder cancer (continued). "Additionally, a related nucleotide, lncRNA H19 has also been classified as an oncogene and promotes bladder cancer metastasis by associating with enhancer of zeste homolog 2 (EZH2) and inhibiting E-cadherin expression." (PMID 36983051, 2023). "Furthermore, ARID1A-deficient bladder cancer was sensitive to combination therapies with EZH2 and PI3K inhibitors in a synergistic manner." (PMID 35852858, 2022). "Thus, we confirmed that sensitivity of bladder cancer cells to EZH2 inhibition is dependent on ARID1A deficiency." (PMID 35852858, 2022). "Thus, our studies suggest that bladder cancers with ARID1A mutations can be treated with inhibitors of EZH2 and/or PI3K and revealed mechanistic insights into the role of noncanonical PI3K constituents in bladder cancer biology." (PMID 35852858, 2022). "We hypothesized that bladder cancer cells with ARID1A mutations would show sensitivity to EZH2 inhibition that could be utilized as a therapeutic target for patients with ARID1A-deficient bladder cancer." (PMID 35852858, 2022). "Investigating the mechanisms of EZH2 sensitivity in ARID1A-deficient bladder cancer cells." (PMID 35852858, 2022). "Thus, there is a rationale to repurpose EZH2 inhibitors for the pharmacologic treatment of patients with bladder cancers harboring somatic truncating mutations in ARID1A." (PMID 35852858, 2022). "Another study showed that the association between the increased expression of H19 and EZH2 enhancers in patients with bladder cancer caused the stimulation of Wnt/p-catenin pathway, resulting in the down-regulation of E-cadherin, thus promoting the metastasis of bladder cancer cells." (PMID 34026626, 2021). "This EZH2 sensitivity in bladder cancer is based on total loss of KDM6A protein." (PMID 30692641, 2019). "Finally, we investigated the putative dependence of ARID1A-depleted and ARID1A-mutated urothelial cells on EZH2 using in vitro models for bladder cancer." (PMID 30138427, 2018). "H19 regulates bladder cancer metastasis through its association with EZH2." (PMID 27903964, 2017). "Exploring these links may help us understand the molecular mechanisms by which KDM2B, EZH2 and genetic alterations associated with bladder cancer may contribute to the oncogenic transformation of the human urothelia." (PMID 28515962, 2017). "Furthermore, another study has found that H19 was remarkably upregulated in bladder cancer tissues, and upregulated H19 promoted cancer cell migration both in vitro and in vivo by associating with EZH2 and inhibiting E-cadherin expression." (PMID 24379988, 2013). "Therefore, targeted EZH2 for the modulation of gene expression could offer therapeutic benefits in the management of bladder cancer characterised by SWI/SNF mutations." (PMID 39779467, 2025). "Therefore, we investigated whether EZH2 inhibition differentially affects bladder cancer cell lines with mutations in either KDM6A alone or both KDM6A and SWI/SNF family members." (PMID 30692641, 2019). "Furthermore, a recent study indicated that upregulated H19 could accelerate bladder cancer metastasis by associating EZH2 and inhibiting expression of -E-cadherin, which was the EMT-induced marker." (PMID 27825121, 2016). "To validate the utility of our PDOs co‐culture model, we employed it to investigate the role of EZH2 in the microenvironment of bladder cancer." (PMID 39921252, 2025). "For example, lncRNA LINC00337 (Lnc-LBCS) has been reported to suppress bladder cancer “stemness” by binding to the chromatin modifier EZH2 and the RNA-binding protein hnRNPK, forming a complex that represses the stem cell gene SOX2." (PMID 40918525, 2025). "In our study, we chose the small molecule compound UNC1999, a dual inhibitor of EZH1 and EZH2, which showed significant efficacy against leukaemia, bladder cancer and colon cancer." (PMID 41372608, 2025).